IZUMO4 (IZUMO family member 4)
Synonyms: C19orf36; IMAGE:4215339
Tractability: Antibody: UniProt places it where antibodies can reach, with high confidence; UniProt predicts a signal peptide or a membrane-spanning region; its Gene Ontology location is reachable by antibodies, with medium confidence.
Gene: Protein-coding gene on chromosome 19 (2,096,429 to 2,099,593, forward strand). Ensembl gene ENSG00000099840.
Subcellular location: Secreted
Subcellular location (Human Protein Atlas): Calyx; Connecting piece; Equatorial segment; Predicted to be secreted
Pathways (Reactome):
Reproduction: Acrosome Reaction and Sperm:Oocyte Membrane Binding
Gene Ontology:
Cellular component: nucleus; extracellular region
Genetic constraint (gnomAD): Loss-of-function variants: 51 observed, 39.1 expected, observed/expected ratio (o/e) 1.3, 90% interval 1.04 to 1.65. The synonymous counts are far from expectation, so gnomAD's model fits this gene poorly and the ratio says little. Missense variants: 364 observed, 313.24 expected, observed/expected ratio (o/e) 1.16, 90% interval 1.07 to 1.27. Synonymous variants: 162 observed, 123.53 expected, observed/expected ratio (o/e) 1.31, 90% interval 1.15 to 1.49.
Homologues: Orthologues: chimpanzee IZUMO4 (98% identical), dog IZUMO4 (83% identical), macaque IZUMO4 (83% identical), pig IZUMO4 (83% identical), rat Izumo4 (75% identical), mouse Izumo4 (74% identical), guinea pig IZUMO4 (73% identical).
Diseases named in the same sentence as IZUMO4 in open-access papers:
IZUMO4 is named in the same sentence as 1 disease in open-access papers, as found by Europe PMC text mining. Sharing a sentence is not in itself a finding about the gene and the disease.
IZUMO4 shares sentences with these, for which no sentence is quoted: lung adenocarcinoma (1 paper).